CTLA4 (cytotoxic T-lymphocyte associated protein 4)
Diseases named in the same sentence as CTLA4 in open-access papers (continued):
Sharing a sentence is not in itself a finding about the gene and the disease.
esophageal cancer (continued). "So far, there is only one report about the expression of CTLA-4 in esophageal cancer, in which the expression level of CTLA-4 protein in primary esophageal cancer lesions has a potential prognostic value." (PMID 31485274, 2019). "The addition of programmed cell death protein-1 (PD-1) inhibitors to chemotherapy (CT) or anti-CTLA4 (ipilimumab) has recently emerged as an effective first-line (1L) treatment for esophageal squamous cell carcinoma (ESCC), the most common form of esophageal cancer globally." (PMID 41567215, 2025). "The safety and efficacy of anti-PD-1 antibodies, including pembrolizumab and nivolumab, for esophageal cancer and the anti-CTLA-4 antibodies (ipilimumab) and anti-PD-1 antibodies (nivolumab) in advanced CTLA-4 in late esophageal cancer have been significantly demonstrated in recent clinical trials." (PMID 36035171, 2022). "Notably, CTLA-4 is typically expressed on immune cells rather than on cancer cells, leaving its role in esophageal cancer cells unclear." (PMID 40136652, 2025). "In the TISIDB database, ENTPD1 expression in esophageal carcinoma was shown to be statistically positively correlated with the expression of currently recognized inhibitory immune checkpoint molecules PDCD1 (p < 0.001), CTLA4 (p < 0.001), and HAVCR2 (p < 0.001)." (PMID 36831526, 2023). "Moreover, our study indicates that EBV and cytomegalovirus elevate PD-L1 or PD-L2, CD80, CD86, PD-1, CTLA-4, Tim-3, LAG3, and 4-1BB expression in multiple cancers along the gastrointestinal tract including stomach and esophageal carcinoma and colon and rectum adenocarcinoma." (PMID 30911684, 2019). "sCTLA-4 was evaluated as a prognostic factor in lung and esophageal cancers, demonstrating that increased post-therapy levels (chemotherapy or radiochemotherapy) correlated with longer OS and PFS, suggesting that this soluble factor may block the classic immunosuppressive activity of CTLA-4." (PMID 39910579, 2025). "Moreover, we found that the expression level of ENTPD1 was positively correlated with the infiltrating abundance of CD8+ T cells and the expression level of inhibitory immune checkpoint molecules PDCD1, CTLA4, and HAVCR2 in esophageal carcinoma, but not in normal tissues." (PMID 36831526, 2023).
inflammatory bowel disease (30 papers, 2009 to 2025). A spectrum of small and large bowel inflammatory diseases of unknown etiology. "One child with CTLA4 deficiency and severe inflammatory bowel disease showed initial improvement followed by recurrence of symptoms despite 100% donor chimerism, hence event-free survival at one year was 96%." (PMID 38200046, 2024). "Consistent with this notion, the SNPs located on the promoter region have been shown to elicit effects on gene expression, The genotypic variants of rs3087243 have been shown to associate with CTLA4 expression in patients with inflammatory bowel disease." (PMID 34671352, 2021). "In the treatment of tumors using CTLA‐4 monoclonal antibody (ipilimumab), the patients showed significant upregulation of the Th1 and Th17 pathways and adverse reactions of inflammatory bowel disease." (PMID 32621335, 2020). "The CTLA4 (cytotoxic T-lymphocyte antigen 4) gene is associated with several immunopathologic diseases and because of its important immuno-regulatory role it may be considered also a plausible candidate for a genetic association with inflammatory bowel diseases." (PMID 20537165, 2010). "Due to suspected inflammatory bowel disease (IBD), a targeted multi-gene panel for primary immunodeficiencies, which includes the most common genetic causes for monogenic IBD was ordered and detected a likely pathogenic variant in CTLA4 (NM_005214.4:c.401T > G; p.(Met134Arg))." (PMID 37353797, 2023). "Nine out of 17 patients had steroids (5–20 mg/d), one had additional anti-TNF-α treatment due to inflammatory bowel disease (XX.II.1), one had additional daclizumab due to MS (CZ.II.2), and two had received abatacept (CTLA4-Fc) additionally in order to ameliorate the CTLA-4 insufficiency." (PMID 30250467, 2018). "For instance, a recent meta-analysis on patients with inflammatory bowel disease (IBD) and cancer found that almost 40% experienced IBD relapse during ICI inhibitor treatment, with CTLA-4 inhibitor use being associated with a higher risk." (PMID 37958291, 2023). "In inflammatory bowel disease (IBD), patients treated with CTLA4-Ig demonstrate minimal improvement and disease exacerbation was seen in some treatment groups." (PMID 26322044, 2015).
multiple sclerosis (30 papers, 2005 to 2026). A progressive autoimmune disorder affecting the central nervous system resulting in demyelination. "The “T” allele of rs5742909 was shown to increase CTLA4 expression and decrease the risk of multiple sclerosis However, the “C” allele of rs5742909 showed an increased risk of TAARs, and it indicated that CTLA4 expression would be altered and cause TAARs." (PMID 31766247, 2019). "In CTLA4 gene, rs221775 the variant is associated with multiple sclerosis susceptibility." (PMID 39854591, 2025). "Furthermore, we confirmed that this synergistic effect is conserved in human T cells from patients with multiple sclerosis (MS) upon CTLA-4 Ig and IL-2 cotreatment." (PMID 42086904, 2026). "This case has significant implications for the development of novel treatments for autoimmune conditions including multiple sclerosis and further emphasises the need for caution with clinical use of CTLA-4 immune checkpoint inhibitors in those with a history of inflammatory demyelination." (PMID 34097529, 2021). "Furthermore, the CTLA‐4 signaling peptide is able to induce human Tregs in vitro and in vivo as well as from peripheral blood mononuclear cells (PBMCs) of multiple sclerosis patients." (PMID 34306974, 2021). "Finally, we investigated whether CTLA‐4 signaling peptide could induce Foxp3 expression in multiple sclerosis (MS) patient PBMCs." (PMID 34306974, 2021). "Abatacept consists of the extracellular domain of CTLA-4 and the Fc region of immunoglobulin G. It can bind with B7 molecules on the surface of antigen-presenting cells and inhibit T-cell activation by blocking the co-stimulatory signals to T cells in multiple sclerosis." (PMID 26372309, 2015). "Interpretation: This is an initial exploration of the utility of CTLA-4, PD-1, TIM-3, LAG-3, and TIGIT expression levels as prognostic indicators in untreated, recently diagnosed multiple sclerosis." (PMID 31134049, 2019). "In multiple sclerosis, N-acetylglucosaminyltransferase I (Mgat1) expression and N-glycan branching are enhanced by vitamin D3 treatment, therefore inhibiting CTLA-4 internalization and increasing the surface expression of CTLA-4 in T-cells." (PMID 39062019, 2024).
myeloma (30 papers, 2014 to 2026). "Here, we analyzed the prevalence of the common LAG3 gene variant rs870849 and the common CTLA4 gene variant rs231775 in myeloma patients eligible for autologous stem cell transplantation." (PMID 41614836, 2025). "Unfortunately, data thus far have shown limited benefit for ICI in Multiple Myeloma, suggesting that polymorphisms within the PD-1 and CTLA-4 genes may play a role in the variability of responses among all hematologic malignancies." (PMID 37920162, 2023). "For instance, blocking CD28 interactions using a CTLA-4 monoclonal antibody (mAb) could prevent the immune escape of myeloma cells and make them more susceptible to CD8+ T cells." (PMID 33562441, 2021). "Studies in the 5T33 murine myeloma model already showed the efficacy of lenalidomide in combination with blockade of other immune checkpoints (e.g. CTLA-4, LAG-3, TIM-3, and combinations thereof)." (PMID 27809856, 2016). "We observed anti-myeloma synergy when mice were treated with anti-PD-L1 and anti-CTLA4 blocking antibodies." (PMID 25614821, 2015). "In this study, we observed the overexpression of FOXP3 and CTLA4 in the BM of myeloma patients when compared to healthy controls." (PMID 25099367, 2014). "Moreover, the median time to subsequent myeloma therapy was significantly lower for patients with CTLA4 rs231775 AA and AG genotype (36.3 months; 95% CI: 33.5-43) than in the patients with GG genotype (not reached; 95% CI 44.6-not reached) (p: 0.01)." (PMID 37122695, 2023). "Also, a phase II study of targeting CD28 in multiple myeloma with abatacept (CTLA4-Ig) determine the therapeutic efficacy to overcome resistance to chemotherapy (NCT03457142)." (PMID 37122695, 2023). "CTLA-4–Ig-transfected J558L murine myeloma,T-cells, isotype control." (PMID 33384695, 2020). "CTLA-4–Ig-transfected J558L murine myeloma,T-cells, isotype controls." (PMID 33384695, 2020). "T-cells, CTLA-4–transfected J558L murine myeloma and isotype controls." (PMID 33384695, 2020). "CTLA-4–Ig-transfected J558L murine myeloma,T-cells and Isotype controls." (PMID 33384695, 2020). "Available data is limited regarding CTLA-4 blockade in patients with plasma cell myeloma." (PMID 28482851, 2017). "We could also confirm enhanced expression of CTLA-4, and we found it to be restricted to bone marrow T cells of myeloma patients." (PMID 27809856, 2016). "Anti-CTLA4 alone also facilitated the elimination of myeloma in approximately 15% of animals." (PMID 25614821, 2015). "The results presented here confirm the hypothesis and show that PD-1/PD-L1 blockade in combination with either TIM-3, LAG-3 or CTLA4 blockade synergistically improves the survival of myeloma bearing mice." (PMID 25614821, 2015). "Therefore, our finding of an increased expression of FOXP3 and CTLA4 in BM of MM patients suggests an accumulation of immunosuppressive Tregs in the tumor microenvironment of myeloma patients." (PMID 25099367, 2014). "We also observed that the inhibitory checkpoint receptor TIGIT is more frequently expressed by BM CD8+ T-cells from myeloma patients than PD-1 and CTLA-4, which supports the hypothesis that TIGIT may play a central role in the immune escape of the malignant plasma cells." (PMID 36131131, 2022). "We here see a similar situation in myeloma bone marrow, i.e., a high proportion of CD8+ T cells which lost CD28 expression and concomitantly gained CTLA-4 expression and upregulated 2B4." (PMID 27809856, 2016). "We observed increased expression of TIM-3, LAG-3, CTLA4, and 2B4 on both CD8 and CD4 T cells in myeloma-bearing mice, and anti-myeloma synergy occurred when the PD-1/PD-L1 axis was blocked in combination with blocking TIM-3, LAG-3, or CTLA4." (PMID 25614821, 2015). "Taken together, we have shown that MM-derived EV promote immunosuppression by modulating the phenotype of lymphoid cells with an increase in the expression of the IC PD-1 and CTLA-4, accompanied by a decrease in CD27 expression, thus facilitating myeloma cell escape and progression." (PMID 35874665, 2022).
myeloma (continued). "Here, we assessed the expression of inhibitory molecules PD-1, CTLA-4, 2B4, CD160, senescence marker CD57, and CD28 on T cells of naive and treated myeloma patients in the bone marrow and peripheral blood and collected data on T cell subset distribution in both compartments." (PMID 27809856, 2016). "Therefore, we assessed surface expression of PD-1, CTLA-4, CD160, and 2B4, as well as expression of CD57 and CD28 in myeloma CD8+ T cells before and after therapy with immunomodulatory drugs and dexamethasone." (PMID 27809856, 2016). "Myeloma-bearing mice were treated with a low dose of whole body irradiation and combinations of blocking antibodies to PD-L1, LAG-3, TIM-3, CD48 (the ligand for 2B4) and CTLA4." (PMID 25614821, 2015). "Similarly, the multiple myeloma cell line, RPMI8226 also found to be CTLA4-FasL resistant, expresses only low surface levels of Fas and CD86, with no CD80." (PMID 25227919, 2014). "In addition, it is known that CD8+ T cells from myeloma patients co-express other immune checkpoints, such as LAG-3, TIM-3, CTLA4, and TIGIT suggesting multiple pathways limiting T-cell responses at this stage of disease and thus explaining the lack of effect from PD-L1/PD-1 blockade as monotherapy." (PMID 33488620, 2020). "A recent study showed that low expression of PD-1, CTLA-4, LAG-3, and TIM-3 is present on T cell clones in bone marrow and peripheral blood samples of myeloma patients, suggesting the T cells are not exhausted." (PMID 28482851, 2017). "PD-L1 is highly expressed on 5T33 myeloma cells, but the ligands for TIM-3 (galectin-9), LAG-3 (MHC class II), and CTLA4 (CD80) are not." (PMID 25614821, 2015).
enteropathy (29 papers, 2017 to 2025). "Abatacept offers a potentially effective treatment for patients with documented CTLA-4 deficiency, inducing and sustaining remission of enteropathy." (PMID 38644452, 2024). "In a younger group of patients with a complex phenotype including CVID, thrombocytopenia, psoriatic arthritis and enteropathy, the detection of a mutation in CTLA4 prompted us to treat them with abatacept, with benefits." (PMID 35327437, 2022). "CTLA-4 haploinsufficiency with autoimmune sequelae, lipopolysaccharide-responsive and beige-like anchor protein deficiency with autoantibodies, Treg defects, autoimmune infiltration, and enteropathy are human genetic disorders associated with deficient CTLA-4 expression and function." (PMID 40861664, 2025). "In some cases, these findings provide clues to the pathogenesis of the complications in CVID, such as mutations in CTLA4, LRBA and BACH2 which have been identified in subjects with severe enteropathy." (PMID 37711607, 2023). "In a cohort of 123 CTLA-4 haploinsufficient patients, abatacept led to an improvement of interstitial lung disease and enteropathy with a response rate above 70%." (PMID 37702894, 2023). "We discuss a case of VEO-IBD in which the patient presented with severe and refractory enteropathy, leading to diagnosis of CTLA-4 haploinsufficiency." (PMID 37205940, 2021). "Based upon encouraging reports describing improvement of ALPS5 enteropathy with CTLA4-Ig treatment and since other therapies had been ineffective, we began subject 1 on a trial of CTLA4-Ig." (PMID 30087679, 2018). "Also, patients with CTLA-4 insufficiency have compromised Treg function, leading to enteropathy and endocrinopathy." (PMID 37235056, 2023). "Abatacept has previously shown beneficial effects in some patients with CTLA-4-insufficiency presenting enteropathy, lymphoproliferation, and autoimmune cytopenias, and in our patient, abatacept was highly effective, leading to fast and sustained improvement of her systemic symptoms." (PMID 37780100, 2023). "Overall, the combined immunodeficiency phenotype with enteropathy and malignancy might suggest a defect within the spectrum of regulatory T-cell disorders (Tregopathy), such as IPEX-like, CTLA4, and LRBA deficiencies." (PMID 35924244, 2022). "The CTLA-4-Fc fusion molecule (abatacept) has been reported to ameliorate manifestations of LRBA deficiency, such as enteropathy and lung disease, which strongly suggests that a loss of proper expression of CTLA-4 is a major pathogenic mechanism underlying immune dysregulation in these patients." (PMID 33795850, 2021). "However, there is accumulating evidence for early alloHSCT being the only curative therapeutic approach for patients suffering from monogenic PIDs causing severe enteropathy, such as IL10/IL10R deficiency, the IPEX syndrome, and CTLA-4 deficiency." (PMID 28197149, 2017). "This does not surprise, considering that about one-third of patients with reported CTLA4-insufficiency suffer from diarrhea, enteropathy, and IBD and that CTLA4 is important in the regulation of intestinal inflammation." (PMID 34599484, 2022). "AIC may occur, but less frequently than in CTLA-4 haploinsufficiency or STAT3-GOF, as with enteropathy and skin manifestations." (PMID 38022498, 2023). "Patients with CTLA-4 insufficiency present heterogeneous clinical manifestations, including hypogammaglobulinemia, cytopenias, autoimmunity, hepatosplenomegaly, enteropathy, and lymphocytic infiltrations of nonlymphoid organs." (PMID 37780100, 2023). "CTLA4 gene haploinsufficiency with autoimmune infiltration (CHAI) leads to broad clinical manifestations such as hypogammaglobulinemia, enteropathy, recurrent infections, lymphocytic infiltration, and multiple autoimmune clinical features, very similar to characteristics of LRBA deficiency." (PMID 28720148, 2017).
enteropathy (continued). "Thus, we present case 1 (CTLA-4 haploinsufficiency) and case 2 (CTLA-4 insufficiency-like phenotype), both manifested with autoimmune cytopenia, enteropathy, and lymphoproliferation, with typical lung and central nervous system (CNS) involvement, and variable impairment of humoral responses." (PMID 36636328, 2022).